DNAJB4 (DnaJ heat shock protein family (Hsp40) member B4)
Diseases named in the same sentence as DNAJB4 in open-access papers (continued):
Sharing a sentence is not in itself a finding about the gene and the disease.
tumor (continued). "In tumor tissues, the phosphorylation levels of STAT3, AKT, and ERK were similar between Dnajb4+/+ and Dnajb4–/– mice, indicating universal activation of these pathways." (PMID 39738726, 2024). "Circ_0009043 acts as a tumor suppressor in NSCLC cells, promoting DNAJB4 upregulation via the sequestration of miR-148a-3p." (PMID 35974419, 2022). "Together, these results revealed that circ_000904 is downregulated in NSCLC cells and that, when expressed, this circRNA can serve as a molecular sponge to sequester miR-148a-3p, thereby leading to DNAJB4 upregulation and the suppression of NSCLC tumor growth." (PMID 35974419, 2022). "Studies have demonstrated that DNAJB4 (HLJ1) and DNAJB6 (MRJ) function as tumor suppressors in multiple types of cancer." (PMID 33966034, 2021). "Although DNAJB4 promoted angiogenesis by increasing CD31 levels, it may also enhance apoptosis in tumor cells through caspase-3-induced apoptosis." (PMID 40149995, 2025). "Notably, DNAJB4 overexpression markedly enhanced CD4 + and CD8 + T cells and reduced PD-L1 levels in 4T1 tumors via the Hippo pathway, which retarded tumor growth in a subcutaneous xenograft tumor mouse model of 4T1 cells." (PMID 37548821, 2023). "Among the 23 HERV-derived miRNAs, hsa-miR-4454, which is derived from the HERV-H family, showed oncogenic traits by targeting the two tumor suppressor genes, DNAJB4 and SASH1, in non-muscle-invasive bladder cancer (NMIBC)." (PMID 38002927, 2023). "Additionally, DNAJB4 protein in the NSCLC tissues was inspected using WB and it was detected that DNAJB4 expression was usually lower in the NSCLC tumor tissue than observed in adjacent tissue." (PMID 35974419, 2022). "This hypothetical functional complex consisting of BAG3, HYOU1, GRB2, UBAP2L and DNAJB4 could be very important in PDAC since, in addition to BAG3, interactors also play an important role in tumor pathology." (PMID 35406724, 2022). "Interestingly, the expression of other DNAJ–HSP40 proteins (DNAJB4 and DNAJB6) that are known as tumor suppressors was increased in metastatic TNBC cell lines." (PMID 33966034, 2021). "DNAJB4 plays a crucial role in tumor cell proliferation and migration, and its overexpression can inhibit tumor progression via the Hippo signaling pathway, indicating its potential as a molecular complement to the TNM system, especially for evaluating tumor aggressiveness and metastatic potential." (PMID 40149995, 2025). "Although the peritumoral expression of p-STAT3 was higher in Dnajb4–/– mice, it shows minimal differences between the tumor sections of Dnajb4–/– and wild-type mice, suggesting another possibility that HLJ1 in the tumor regions may regulate tumor proliferation in a STAT3-independent manner." (PMID 39738726, 2024). "In normal tissues, lower p-STAT3 levels in Dnajb4+/+ mice compared to Dnajb4–/– mice suggest that the absence of HLJ1 may enable sustained tumor progression." (PMID 39738726, 2024). "Since STAT3 phosphorylation (p-STAT3) can occur in response to cytokine IL-6 secreted by macrophages during DEN-induced tumor initiation and thus reflect liver inflammation, we investigated whether p-STAT3 levels were altered in Dnajb4–/– mice post-DEN injection." (PMID 39738726, 2024). "In addition, our study also identified NR2F1, DNAJB4, and STON2 as the downregulated genes in SN, which could suppress tumor growth and metastasis." (PMID 34722496, 2021). "Altogether, 151 up- and 64 down-regulated genes were identified between UVB-irradiated and non-irradiated skin biopsies, among which down-regulated DNAJB4 and SLIT2 were annotated as tumor-suppressors and up-regulated KIT was annotated as an oncogene." (PMID 27829444, 2016).
cancer (18 papers, 2011 to 2025). A tumor composed of atypical neoplastic, often pleomorphic cells that invade other tissues. "The current study showed that high DNAJB4 expression was a risk factor for increased CD31 levels but was negatively correlated with advanced-stage cancer." (PMID 40149995, 2025). "However, among the patients with late-stage cancer, high DNAJB4 expression was significantly associated with increased levels of caspase-3 (OR: 1.20, p = 0.013), CD31 (OR: 1.06, p = 0.004), and EphA5 (OR: 1.04, p = 0.033), but it was negatively correlated with E-cad expression (OR: 0.93, p = 0.011)." (PMID 40149995, 2025). "In our study, high DNAJB4 expression increased CD31 expression but was negatively correlated with advanced-stage cancer." (PMID 40149995, 2025). "The strength of our study lies in its multivariate analysis, the results of which emphasize that high CD31 levels and advanced cancer stage are strong predictors of outcomes and have an independent relationship with DNAJB4 expression." (PMID 40149995, 2025). "Two studies have presented DNAJB4 as a potential target for cancer therapy because of its influence on protein folding and degradation, particularly its interaction with mutated proteins and its effects on cellular functions (e.g., adhesion)." (PMID 40149995, 2025). "Several key differences emerged in the comparison between high and low DNAJB4 expression among patients with early- and late-stage cancers." (PMID 40149995, 2025). "DNAJB4 promotes the stabilization of wild-type E-cad, enhances cell adhesion, and inhibits cancer cell invasiveness." (PMID 40149995, 2025). "Among the patients with early-stage cancer, males were significantly more likely to have high DNAJB4 expression than females (OR: 9.61, p = 0.042)." (PMID 40149995, 2025). "The first one regarding increased carcinoma incidence was significantly positively enriched in Dnajb4–/– mice, with 19 of 40 core-enriched genes identified." (PMID 39738726, 2024). "Combined expression of YY1 and AP-1 can enhance DNAJB4 expression and suppress cancer cell proliferation, angiogenesis, and metastasis." (PMID 36499297, 2022). "DNAJB4 expression was lower in tumors than adjacent normal tissues and patients with high DNAJB4 expression tumors had reduced cancer recurrence and longer survival than those with lower expressing tumors." (PMID 21255413, 2011). "Third, although DNAJB4 expression was analyzed and its relationship with other proteins and patient outcomes was investigated, the specific molecular mechanisms by which DNAJB4 affected cancer progression, angiogenesis, and apoptosis remained unclear, thus requiring further functional studies." (PMID 40149995, 2025). "Therefore, overexpression of DNAJB4 can suppress cancer progression and invasion and is considered a cancer biomarker or a promising target for anticancer therapy." (PMID 37510314, 2023). "Importantly, some DNAJB proteins, including DNAJB1/HDJ1, DNAJB4/HLJ1, DNAJB6/MRJ, DNAJB8, DNAJB9/MDG1/ERdj4, DNAJB11/ERdj3/HEDJ, and DNAJB12, are implicated in cancer progression." (PMID 34948322, 2021). "The results of UALCAN database analysis showed that the mRNA expression levels of CALR, CREB3L3, FBOX6, and KDELR3 were increased in cancer tissues compared with normal tissues, while the mRNA expression levels of CRYAB, DNAJB4, and HSPB6 were decreased in BLCA." (PMID 34930465, 2021).
myopathy (4 papers, 2024). A disease of the muscle in which the muscle fibers do not function properly. "Recent studies have highlighted the association of DNAJB4 variants with both recessive and dominant forms of myopathy." (PMID 39468638, 2024). "Within this context, several references in the literature link the loss of function and dominant variants of DNAJB4 to myopathy." (PMID 38392191, 2024). "While muscle biopsies were not available for all patients, limiting direct pathological examinations, we successfully utilized cell-based models to assess myopathy-associated DNAJB4 variants." (PMID 39468638, 2024). "Following the 1-hour heat shock, cells expressing myopathy-associated DNAJB4 variants exhibited an increased percentage of cells with aggregates compared with those expressing DNAJB4-WT." (PMID 39468638, 2024). "We previously reported that pathogenic variants in both DNAJB4 and its homolog DNAJB6, which are associated with myopathy, alter the aggregation and disaggregation of their putative client protein, TDP-43." (PMID 39468638, 2024). "Despite these advancements, many aspects of DNAJB4 myopathy remain poorly understood." (PMID 39468638, 2024). "This study provides insight into the genotype‒phenotype correlation in DNAJB4 myopathy." (PMID 39468638, 2024). "Within this context, our analysis revealed correlations with several proteins, including BAG5, DNAJB4, and DNAJB5, which have plausible or confirmed roles in myopathy." (PMID 38392191, 2024).
neurodegenerative disease (1 paper, 2023). A disorder of the central nervous system characterized by gradual and progressive loss of neural tissue and neurologic function. "JDPs have previously been implicated in various neurodegenerative diseases, with prior work suggesting that DnaJA2, DnaJB1, and DnaJB4 suppress tau aggregation in vitro." (PMID 37387473, 2023).
neuromuscular disease (1 paper, 2024). "Dominant variants of DNAJB4 are associated with skeletal muscle and neuromuscular diseases." (PMID 38392191, 2024).
DNAJB4 also shares sentences with these, for which no sentence is quoted: Bladder Cancer (1 paper); bladder urothelial carcinoma (1); breast tumor (1); cardiovascular diseases (1); coagulation disorders (1); colon adenocarcinoma (1); diabetes (1); heart diseases (1); infection (1); limb-girdle muscular dystrophy (1); lung squamous cell carcinoma (1); metabolic disease (1); myocardial infarction (1); pancreatic cancer (1); rheumatoid arthritis (1); skin cancer (1); viral infections (1).